SERPINA1 (serpin family A member 1)
Diseases named in the same sentence as SERPINA1 in open-access papers (continued):
Sharing a sentence is not in itself a finding about the gene and the disease.
Alpha-1-antitrypsin deficiency (91 papers, 2008 to 2026). "Alpha-1 antitrypsin deficiency (AATD) is an autosomal co-dominant condition caused by mutations in the SERPINA1 gene." (PMID 41578478, 2026). "Mutations in the SERPINA1 gene, which encodes alpha-1 antitrypsin, are the most well-characterized genetic risk factors, leading to hereditary alpha-1 antitrypsin deficiency (AATD)." (PMID 40688081, 2025). "Alpha-1 antitrypsin deficiency (AATD) is an autosomal recessive disorder caused by mutations in the SERPINA1 gene (AAT)." (PMID 40507182, 2025). "Alpha-1 antitrypsin deficiency (AATD) is an autosomal codominant inherited condition caused by mutations in the SERPINA1 gene." (PMID 41450890, 2025). "Alpha-1 antitrypsin deficiency (AATD) is a rare autosomal co-dominant disease caused by mutations in the SERPINA1 gene." (PMID 39492455, 2024). "Most frequent variants of SERPINA1 gene leading to alpha-1-antitrypsin deficiency — rs28929474 (c.1096G>A, p.Glu366Lys, PIZ), rs17580 (c.863A>T, p.Glu288Val, PIS)." (PMID 39881831, 2024). "Alpha-1 antitrypsin deficiency (AATD) is a genetic disorder caused by specific variants in the SERPINA1 gene, which encodes AAT." (PMID 40225912, 2024). "Predicting the clinical significance of SERPINA1 variation allows clinicians to tailor treatment options for individuals with alpha-1 antitrypsin deficiency (AATD) and related conditions, ultimately improving the patient’s outcome and quality of life." (PMID 38540399, 2024). "Alpha-1 antitrypsin deficiency (AATD) is caused by mutations in SERPINA1, the gene encoding alpha-1 antitrypsin (AAT)." (PMID 38360172, 2024). "Alpha-1-antitrypsin deficiency (AATD) is a genetic disorder characterized by mutations in the SERPINA1 gene, primarily affecting the lungs and liver." (PMID 37880685, 2023). "Alpha-1-antitrypsin deficiency (AATD) is a genetic disorder that results in a reduced concentration of alpha-1-antitrypsin (AAT) in the body due to a mutation in the SERPINA1 gene." (PMID 37880685, 2023). "Alpha-1 antitrypsin deficiency (AATD) is an excellent example of such interplay with the highly polymorphic SERPINA1 gene product, which, similar to other serpins, is prone to conformational shifts and therefore significant changes in its functionality." (PMID 36902496, 2023). "Alpha-1 antitrypsin deficiency (AATD) is an autosomal recessive Mendelian genetic disorder caused by reduced abundance or dysfunction of the alpha-1 antitrypsin (A1A) protein, encoded by SERPINA1." (PMID 37651384, 2023). "Alpha-1 antitrypsin deficiency (AATD) is a genetic illness caused by a single nucleotide mutation in the SERPINA1 gene." (PMID 36068572, 2022). "Pathogenic variants in the SERPINA1 gene underlie alpha-1-antitrypsin deficiency (A1ATD), which causes reduced protein levels." (PMID 36504721, 2022). "Mutations of the genes involved in hemochromatosis, alpha 1-antitrypsin deficiency (SERPINA1), glycogen storage diseases (G6PC, SLC37A4), porphyries (HMBS, UROD), tyrosinemia (FAH), and Wilson’s Disease (ATP7B) increase the susceptibility to HCC." (PMID 36676960, 2022). "Alpha-1-antitrypsin deficiency (AATD) is an inherited condition caused by mutations in the SERPINA1 gene that negatively affect AAT level and/or activity." (PMID 36186645, 2022). "Alpha-1 antitrypsin deficiency (AATD) is a rare genetic condition caused by mutations on the SERPINA1 gene, which is responsible for expression of the protein alpha-1 antitrypsin (AAT)." (PMID 32784514, 2020). "Certainly, pSAD-based minigenes represented valuable tools to functionally check variants of the SERPINA1 (severe alpha-1 antitrypsin deficiency) and CHD7 (Charge Syndrome) genes." (PMID 29881398, 2018). "Severe Pi*ZZ alpha-1 antitrypsin (AAT) deficiency, caused by the Glu342Lys mutation in the SERPINA1 gene, resulting in protein misfolding and polymerization in hepatocytes, and proteotoxic stress which may lead to progressive liver injury." (PMID 41450890, 2025).
Alpha-1-antitrypsin deficiency (continued). "Alpha-1 antitrypsin deficiency (AATD) is an inherited disease caused by SERPINA1 gene mutations." (PMID 39298444, 2024). "Alpha 1-Antitrypsin Deficiency (AATD) is a rare genetic disorder caused by mutations in the SERPINA1 gene, which encodes the Alpha 1-Antitrypsin (AAT) protein." (PMID 41272759, 2025). "Alpha 1-antitrypsin deficiency (AATD) is a genetic disease caused by a mutation in the SERPINA1 gene (serine proteinase inhibitor, group A, member 1), which encodes a secretory protein, alpha 1-antitrypsin (AAT)." (PMID 32754041, 2020). "The robust editing capabilities of PE present substantial therapeutic potential; for example, in a mouse model of Alpha-1 antitrypsin deficiency (AATD), PE successfully eliminated the pathogenic E342K mutation in SERPINA1 by executing A-to-G edits." (PMID 40697666, 2025). "Alpha-1 antitrypsin deficiency (AATD) is a rare genetic condition inherited in a codominant manner, caused by mutations in the SERPINA1 gene." (PMID 41155753, 2025). "Alpha-1 antitrypsin deficiency (AATD) is one of the most common genetic disorders in adults and is characterized by reduced levels of circulating alpha-1 antitrypsin (AAT), attributed to mutations within the SERPINA1 gene." (PMID 38926693, 2024). "Alpha-1 antitrypsin deficiency (AATD) is an inherited disease, the common variant caused by a Pi*Z mutation in the SERPINA1 gene." (PMID 39298444, 2024). "For example, alpha-1 antitrypsin (encoded by SERPINA1) and carbamoyl phosphate synthetase I (encoded by CPS1) are involved in human Alpha-1 antitrypsin deficiency and CPS1 deficiency, respectively." (PMID 35866031, 2022). "Alpha-1 antitrypsin deficiency (AATD) is caused by a single mutation in the SERPINA1 gene, which culminates in the accumulation of misfolded alpha-1 antitrypsin (ZAAT) within the endoplasmic reticulum (ER) of hepatocytes." (PMID 34948056, 2021). "Two prime examples are the variants in SERPINA1 and HFE responsible for alpha-1 antitrypsin deficiency and hereditary hemochromatosis that are relatively common in individuals of European ancestry but rare in East Asians." (PMID 33547301, 2021). "Several mutations can affect the SERPINA1 gene and lead to alpha 1-antitrypsin deficiency (AATD)." (PMID 33668611, 2021). "Alpha-1 antitrypsin deficiency (AATD) is a common hereditary disorder caused by mutations in the SERPINA1 gene, which encodes alpha-1 antitrypsin (AAT; also known as alpha 1-proteinase inhibitor, A1-PI)." (PMID 28558837, 2017). "Alpha-1 antitrypsin deficiency (AATD) (MIM # 613490) is an inherited condition caused by mutations within the polymorphic SERPINA1 gene and is characterised by decreased serum AAT concentrations." (PMID 25425243, 2014). "In addition to alpha-1 antitrypsin deficiency (AATD), which is caused by variants in SERPINA1 (serpin family A, member 1), there are several other genetic loci related to lung function decline or COPD risk that have been reported." (PMID 36291689, 2022). "By analogy with cholestasis in children with inherited alpha-1 antitrypsin deficiency (AATD), we hypothesized the SERPINA1 Z pathogenic variant might be related to a higher risk of cholestasis in pregnancy." (PMID 34557220, 2021). "Alpha-1 antitrypsin deficiency (A1ATD) is a rare genetic condition in both humans and animals, caused by mutations in the SERPINA1 gene that lead to reduced or absent production of alpha-1 antitrypsin (A1AT)." (PMID 41230463, 2025).
COVID-19 (72 papers, 2020 to 2025). A disease caused by infection with severe acute respiratory syndrome coronavirus 2. "Independent investigations have also found that genes related with some of these transcripts (IGI27, SEMA4D, SIGLEC1, and SERPINA1) are repressed in severe COVID-19, underlining their potential as early predictors of severity." (PMID 37918965, 2024). "In this study, our results provide genetic evidence to suggest that increased SERPINA1 level reduced risk of COVID-19 severity in African ancestry." (PMID 35772218, 2022). "In vitro transcriptomic data derived from 3D lung model, people who are less susceptible to COVID-19 express higher levels of antiprotease genes including SERPINA-1." (PMID 36671467, 2022). "In April 2020, a geographical overlap between the prevalence of allelic variants of SERPINA1 and severe cases of COVID-19 was reported in Italy." (PMID 34640510, 2021). "In addition, SerpinA1 was associated with decreased COVID-19 severity, and suggested as a potential COVID-19 treatment." (PMID 38760690, 2024). "Also, according to IPA analysis, some of them have been associated with viral infection (APOD, APOH, SERPINA1), severe COVID-19 (APOD, APOH, PCYOX1), or leukocyte migration (APOD, IGHV3-13, IGHV3-23, SERPINA1, IGLC7, IGLV3-21)." (PMID 35397534, 2022). "This analysis demonstrates that, having mutations, variants of the SERPINA1 gene that could affect A1AT protein activity or expression and that having decreased A1AT levels was significantly associated with a higher likelihood of suffering from a severe COVID-19 case." (PMID 36831051, 2023). "This implies that increased SERPINA1 levels may reduce COVID-19 risk in Africans." (PMID 35772218, 2022). "A recent study revealed that SERPINF2 expression increases in serum levels of patients with COVID-19, along with several other SERPINs (SERPINA1 and SERPINA3)." (PMID 36690780, 2023). "The beneficial effect of increased SERPINA1 on COVID-19, especially in Africans, is worth careful investigation in future studies." (PMID 35772218, 2022). "Our study identified one protein, SERPINA1, that showed effects on COVID-19 in African ancestry (OR=0.369, P = 9.96 × 10−4), but weaker in European ancestry (OR=1.021, P = 0.745)." (PMID 35772218, 2022). "Targeting N6-methyladenosine (m6A) pathways (e.g., METTL3/SERPINA1 axis) to restrict SARS-CoV-2 reproduction has therapeutic potential for COVID-19 patients." (PMID 36555339, 2022). "A clinical trial testing SERPINA1/alpha-1 antitrypsin for the treatment of COVID-19 has recently been started (ClinicalTrials.gov Identifier: NCT04385836)." (PMID 33143316, 2020). "In line with a previous study, SerpinA1 was downregulated in our COVID-19 cohort." (PMID 38760690, 2024). "Indeed, COVID-19 patients with moderate to severe acute respiratory distress syndrome improved in a phase 2 randomized control trial after SerpinA1 intervention." (PMID 38760690, 2024). "In a large genome-wide association study (GWAS) meta-analysis of over 125 000 COVID-19 cases and 2.5 million controls, SERPINA1 (AAT) gene polymorphism was not identified to be a major associative factor for severe COVID-19." (PMID 37294003, 2023). "OAS1 and SERPINA1 were targets of existing drugs in trials as potential COVID-19 treatments." (PMID 35772218, 2022). "The SERPINA1 gene is a serine protease inhibitor, alpha-1 antitrypsin, that may protect against COVID-19 by inhibiting TMPRSS2." (PMID 35772218, 2022). "Linkage disequilibrium (LD) analysis for rs28929474 and rs17580 in the SERPINA1 gene in the study population showed that these two genetic variants were not in LD in patients with severe COVID-19 survivors and non-survivors." (PMID 35892712, 2022). "Moreover, when we compared the proteomes of critically ill COVID-19 patients who eventually deceased due to the infection to those who could be discharged from hospital, we found SERPINA1 among the factors that were higher expressed in the survivors." (PMID 37293294, 2023).
COVID-19 (continued). "Factors associated with a higher likelihood of severe COVID-19 were being male, older, smoking, age-associated comorbidities, and having an A1AT level below 116 mg/dL [OR 1.398, p = 0.003], and a variant of the SERPINA1 gene that could affect A1AT protein [OR 1.294, p = 0.022]." (PMID 36831051, 2023). "SERPINA1 showed an effect on COVID-19 severity in African ancestry using the GenOMICC v2 data (OR=0.481, 95%CI=0.345 to 0.673, P = 1.9 × 10−5), where the heterogeneity test suggested a distinct effect estimate of SERPINA1 across the two ancestries (P of pair-wise Z-score test=7.70 × 10−6)." (PMID 35772218, 2022). "Interestingly, SERPINA1 (encoding protease inhibitor α-1 antitrypsin) and PFKFB3 (encoding phosphofructokinase, a key regulator of glycolysis) were suppressed in COVID-19 neutrophils, suggesting divergence in granule-associated enzyme composition and metabolic states." (PMID 34782790, 2022). "Increased serum NE activity was detected during severe COVID-19, despite the functional inhibitory activity of serpinA1 against exogenous soluble NE, thereby revealing a mechanism of resistance of NET-derived NE to serpinA1 that may be relevant during COVID-19." (PMID 34031543, 2021). "The inflammatory factors SAA2, SAA1, SERPINA1, and SERPINA3 are significantly upregulated proteins in the sera of the severe COVID-19 patients." (PMID 38638822, 2024). "The OAS1, SERPINA1 and ICAM1 effects were replicated using updated COVID-19 severity data in the two ancestries respectively, where alternative splicing events in OAS1 and ICAM1 also showed marginal effects on COVID-19 severity in Europeans." (PMID 35772218, 2022). "Several altered proteins in the serum of COVID-19 positive asymptomatic donors (FGA, SERPINA1, THBS1) and moreover, in CACs treated with these serum factors (HSPA5, FN1), have been associated with platelet aggregation and coagulation problems." (PMID 35397534, 2022). "Based on our data, however, SERPINA1/alpha-1 antitrypsin is not expected to exert direct antiviral effects in COVID-19 patients." (PMID 33143316, 2020). "Notably, SERPINA1/alpha-1 antitrypsin was shown to inhibit TMPRSS2 in an enzymatic assay and is suggested as an antiviral treatment for COVID-19." (PMID 33143316, 2020). "The observed increase in levels of SERPINA1 and SERPINA3 might therefore partly reflect the more stable, chemoattractant, pro-inflammatory cleaved forms, rather than the short-lived tissue-protective proteins in severe COVID-19." (PMID 34139154, 2021). "It is also possible to hypothesize that some SERPINA1 deficient allelic variants could not allow AAT to be sufficiently increased or efficient to counteract SARS-CoV-2 infection, leading to the progressive worsening of the COVID-19 disease." (PMID 33195215, 2020). "A number of proteins identified as outcome predictors have also been shown to be differentially expressed in sepsis, including SAA1, CRP, SERPINA1, KLKB1, and A2M, indicating a general inflammatory signature rather than specific markers of COVID-19." (PMID 36812516, 2022).
Cirrhosis (69 papers, 2009 to 2026). A chronic disorder of the liver in which liver tissue becomes scarred and is partially replaced by regenerative nodules and fibrotic tissue resulting in loss of liver function. "The SERPINA1 variant is a known cause of α-1 antitrypsin deficiency, which confers a higher risk of cirrhosis and, in turn, HCC." (PMID 40823170, 2025). "The heterozygous presence of a1-antitrypsin mutations from the SERPINA1 gene elevates the risk of chronic liver disease and cirrhosis, and a1-Antitrypsin deficiency is a prevalent genetic disorder impacting both lung and liver." (PMID 40004054, 2025). "Recent research indicates a connection between SERPINA1 Pi*Z and increased disease severity and cirrhosis risk in NAFLD and ALD patients." (PMID 40004054, 2025). "For example, the well‐known rs28929474:T allele in SERPINA1 is associated with higher albumin levels (implying lower disease risk), but at the same time, it is strongly associated with a higher risk of cirrhosis." (PMID 39425533, 2024). "The variants at HFE and SERPINA1 cause hemochromatosis and α-1 antitrypsin deficiency, respectively, well-known risk factors for cirrhosis." (PMID 38632349, 2024). "Early autopsy studies suggested that about one-third of patients homozygous for the Pi∗Z allele (serpin family A member 1 [SERPINA1] rs28929474[T]) develop cirrhosis." (PMID 36176936, 2022). "Our study demonstrates that CVID patients with defective SERPINA1 variants may display a higher probability of developing hepatic complications, ranging from elevated liver enzymes to cirrhosis." (PMID 38791420, 2024). "Moreover, α1-antitrypsin (encoded by SERPINA1), an inhibitor of neutrophil elastase, whose gene variants are associated with severity of fatty liver disease, liver fibrosis and cirrhosis, was also upregulated in aged liver." (PMID 37378670, 2024). "The SERPINA1 variant was only associated with all-cause cirrhosis in a recessive model." (PMID 32247823, 2020). "The frequency of SERPINA1 MZ heterozygotes was significantly higher (p < 0.0001) in the entire cirrhosis group (84/1583; 5.3%) than in controls (89/3483; 2.6%), OR 2.57 (95% CI 1.92–3.44)." (PMID 41004464, 2025). "The rate of individuals with SERPINA1 MZ genotypes was significantly higher among the patients with cirrhosis related to harmful alcohol consumption and metabolic dysfunction-associated steatotic liver disease." (PMID 41004464, 2025). "The frequency of SERPINA1 MZ genotype was significantly higher (p < 0.0001) in the cirrhosis group (84 of 1583; 5.3%) than in controls (89 of 3483; 2.6%)." (PMID 41004464, 2025). "Additional genetic loci implicated in cirrhosis progression risks include HMBS, MAFB, CENPW, EFNA1, and SERPINA1, among others." (PMID 40004054, 2025). "Of those, we found that rs72613567 in HSD17B13 and known risk variants in SERPINA1 (p.Glu366Lys) and HFE (p.Cys282Tyr) exhibited stronger effects on cirrhosis than on NAFLD." (PMID 38632349, 2024). "In the liver, the main site of the synthesis of SERPINA1, defective SERPINA1 molecules accumulate and aggregate into higher-order polymers that induce fibrosis and cirrhosis." (PMID 38338354, 2024). "The frequency of the SERPINA1 MZ genotype was significantly higher (p < 0.0001) in the cirrhosis group (55 of 1119; 4.92%) than in the controls (87 of 3240; 2.69%)." (PMID 34638908, 2021). "The specificity of variant-metabolite associations were compared to metabolite associations with ultrasound-defined steatosis, gene variants linked to liver fat (in GCKR, PPP1R3B and LYPLAL1) and gene variants linked to cirrhosis (in HFE and SERPINA1)." (PMID 32720691, 2020). "In addition to cirrhosis, the amount of SERPINA1 secreted from hepatocytes into the bloodstream is reduced, leading to tissue destruction in the lungs due to excessive neutrophil elastase activity." (PMID 39749860, 2025).
Cirrhosis (continued). "We examined the association of all-cause cirrhosis with six genetic variants previously reported to be associated with alcoholic or non-alcoholic cirrhosis: PNPLA3 I48M, TM6SF2 E167K, MBOAT7 rs641738, HSD17B13 rs72613567, HFE C282Y and SERPINA1 E366K." (PMID 32282858, 2020). "Pathogenic variations in SERPINA1 (α1‐antitrypsin) (MIM 613490) result in the formation of a polymer of variant SERPINA1 in the rough endoplasmic reticulum in hepatocytes that produce SERPINA1, which ultimately leads to cell damage, liver injury, and cirrhosis." (PMID 39749860, 2025). "The germline genetic testing was limited to the 226 cancer-predisposition genes included in the CZECANCA panel, which was designed for the analysis of cancer predisposition but does not cover some of the known cirrhosis-predisposing genes (i.e., APOB, HFE, PNPLA3, SERPINA1)." (PMID 36612198, 2022).